ENSG00000230615 (novel transcript)
Synonyms: LOC107984948
Gene: Long non-coding RNA gene on chromosome 1 (44,030,414 to 44,115,913, forward strand). Ensembl gene ENSG00000230615.
Gene Ontology:
Biological process: SRP-dependent cotranslational protein targeting to membrane, signal sequence recognition
Cellular component: signal recognition particle, endoplasmic reticulum targeting